SDC2 (syndecan 2)
Diseases named in the same sentence as SDC2 in open-access papers (continued):
Sharing a sentence is not in itself a finding about the gene and the disease.
cancer (77 papers, 2008 to 2025). A tumor composed of atypical neoplastic, often pleomorphic cells that invade other tissues. "Conversely, cancer-associated fibroblasts communicate with epithelial cancer cells via MDK targeting SDC2/SDC4/NCL on the epithelial cell surface." (PMID 40429950, 2025). "SDC2 is a versatile heparan sulfate proteoglycan involved in various cellular functions and implicated in cancer biology and inflammation." (PMID 39684750, 2024). "A significant increase in syndecan-2 staining intensity was observed in lymph nodes compared to primary tumors, suggesting that syndecan-2 associates with metastasis during the course of cancer progression." (PMID 25623282, 2015). "Although much less studied, SDC2 has also been reported to be associated with malignant carcinoma lesions in various anatomical sites/organs including head and neck." (PMID 25935541, 2015). "SDC2 serves as a docking receptor for matrix metalloproteinase (MMP)-7 in cancer cells, an enzyme implicated in the pathogenesis of fibrosis." (PMID 22900087, 2012). "Oncogenic potential of SDC2 has been implicated in multiple types of cancers, yet its role and underlying molecular mechanisms in GC remain unknown." (PMID 37496999, 2023). "Syndecan-2 has been implicated in diverse cellular events, including highly dynamic processes such as angiogenesis and cancer metastasis, but also in formation of mature structures like dendritic spines and control of ECM assembly, all of which appear to require the intact cytoplasmic domain." (PMID 32984315, 2020). "Indeed, shed syndecan-2 from cancer-conditioned media and recombinant shed syndecan-2 enhanced cancer-associated activities, and depletion of shed syndecan-2 abolished these effects." (PMID 25686828, 2015). "Similarly, shed syndecan-2 was detected from sera of patients from advanced carcinoma (625.9 ng/ml) and promoted cancer-associated activities." (PMID 25686828, 2015). "As this is not the interaction site for CD148, our results suggest that unique regulatory mechanisms may be involved in syndecan-2 shedding and the associated regulation of cancer activity." (PMID 25686828, 2015). "SDC2 was listed as a high-risk gene for cancer in the TCGA database." (PMID 23131872, 2012). "A previous study has demonstrated that the SDC2 regulates intracellular signaling by directly interacting with FN and that interaction enhances cancer cell adhesion and dissemination." (PMID 40940401, 2025). "KEGG pathway analysis revealed that both SDC2 and FN were enriched in the proteoglycans in cancer pathway (P < 0.0001)." (PMID 40940401, 2025). "KEGG pathway analysis manifested that SDC2 was mainly linked with cell adhesion and FN with ECM-receptor interaction, as well as both being associated with the proteoglycans in cancer pathway." (PMID 40940401, 2025). "Another receptor on the cell membrane of CAFs, MDK, interacts with NCL/SDC2/SDC on cancer cells, potentially serving as therapeutic targets." (PMID 38720108, 2024). "The SDC2 downstream genes in the pathway of proteoglycans in cancer also showed relatively high expression levels in hc10." (PMID 38472225, 2024). "Previous studies have reported that SDC2 was overexpressed and enhanced invasion in several cancers." (PMID 37358427, 2023). "SDC2, the hub immune-related gene, was proved to be differently expressed gene in various cancers using the UALCAN database." (PMID 35127947, 2022). "Syndecan-2 (SDC2), as one of the syndecan family of heparan sulfate proteoglycan, has been demonstrated to play an important role in cancer progression through regulation of cell adhesion, proliferation, and migration in many studies." (PMID 35227195, 2022). "Among the top CellChat interactions, we identified MDK from CAFs targeting SDC2/SDC4/NCL of cancer cells." (PMID 36352420, 2022).
cancer (continued). "Collagens, MIF, MDK, APP, and laminin were detected as the most significant signaling, and the top ligand-receptor interactions THBS2/THBS3 (CAFs)—CD47 (cancer cells), MDK (CAFs)—NCL/SDC2/SDC4 (cancer cells) as potential therapeutic targets." (PMID 36352420, 2022). "Considering that the left and right colons manifested significant differences in tissue origin, cancer pathogenesis, and clinical prognosis, it is easy to interpret that SDC2 was differentially methylated among the different locations." (PMID 33955718, 2021). "In tissue sample testing, the 2−ΔΔCt value showed a tendency of normal < cancer (p < 0.001) for either SDC2 or TFPI2." (PMID 35004840, 2021). "In the same type of cancer, SDC2 also mediates IGF-I-induced activation of the ERK pathway facilitating cell migration." (PMID 32916872, 2020). "This is exemplified in the enrichment of cancer-associated metabolic and proliferative events, such as integrin signaling, IF1/2-mediated events, Syndecan-2-mediated signaling and uPA/uPAR-mediated signaling, and MYC and associated transcription factors." (PMID 32885042, 2020). "The SEPT9 and SDC2 methylation levels were higher in 94.7% (18/19) and 100.0% (19/19) of cancer tissues than in their paired adjacent paracancer tissues (p < 0.001), thus making the ColoDefense assay a candidate method for CRC screening." (PMID 31089394, 2019). "Our results suggest that syndecan-2-mediated regulation of cancer activity depends on its interaction with and activation of MMP-7." (PMID 31337828, 2019). "SEPT9 and SDC2 methylation levels were higher in 92.5% (37/40) and 97.5% (39/40) of cancer tissues than in their paired adjacent paracancerous tissues (P < .01)." (PMID 31407497, 2019). "This reduced enzymatic activity was associated with reduced extracellular domain shedding of syndecan-2 and E-cadherin, which are well-known substrates for MMP-7 in cancer cells." (PMID 31337828, 2019). "SEPT9 and SDC2 methylation levels were higher in 94.7% and 100.0% of cancer tissues than in their paired adjacent tissues." (PMID 31089394, 2019). "Subsequently they confirmed that SDC2 methylation was evident in 80% or more of the tested cancer tissues by qMSP." (PMID 29225717, 2017). "Syndecan-2 (SDC2) is a heparan-sulfate glycosaminoglycan, which participates in cell adhesion and migration, and is known to play a role in cancer progression and neoangiogenesis." (PMID 26042506, 2015). "Expression of the cell surface adhesion receptor SDC2 is increased in a variety of cancers and correlated with progression and poor prognosis." (PMID 26576639, 2015). "However, it remains unclear how shed syndecan-2 could regulate cancer associated activities." (PMID 25686828, 2015). "In contrast, other gene pairs, e.g. GRASP and NPY, or IRX1 and GRASP, or IRX1 and SDC2, are commonly methylated but show little correlation in measured levels of methylation within individual cancer samples." (PMID 24485021, 2014). "While in 48 tissues, peritumoral SDC-2 expression was found (out of these, a minority also showed cytoplasmatic cancer cell staining), in 24 tissues there was SDC-2 positivity in the cytoplasm of the cancer cells." (PMID 22471946, 2012). "Interestingly, binary effect of SDC2 was found in different tumors which correlated with the tissue origin and cancer subtypes." (PMID 35127947, 2022). "Previous studies have shown that SDC2 has a higher methylation level in cancer tissues, which indirectly supports our hypothesis." (PMID 34098960, 2021). "The purpose of the present study was to investigate the role of a stool DNA test targeting methylated SDC2 that is frequently methylated in CRC, which is a leading cause of cancer-related morbidity and mortality, as a potential noninvasive detection tool for the disease." (PMID 33393623, 2021).
cancer (continued). "It has been recently shown that LMP1 promotes EVs secretion and may enhance cancer progression and metastasis by up-regulating syndecan-2 (SDC2) and synaptotagmin-like-4 (SYTL4) through nuclear factor (NF)-κB signaling." (PMID 32521696, 2020). "High level expression of syndecan-2 has been observed in many cancers." (PMID 31249810, 2019). "Moreover, the translocation of syndecan-2 to lipid rafts induced by tubulin polymerization can also regulate cancer cell migration." (PMID 30135409, 2018). "During cancer progression, syndecan-2 expression is also altered." (PMID 30135409, 2018). "Indeed, it was recently discussed that the role of the HSPG, syndecan-2 in cancer pathogenesis is conditional on cancer tissue origin determining its use as a biomarker/therapeutic target feasible." (PMID 29559954, 2018). "One of the best examples of syndecan-2 functions is its regulatory role in cancer progression." (PMID 25686828, 2015). "Sdc2 plays a critical role as an adhesion receptor during cancer cell migration." (PMID 23131872, 2012). "Furthermore, SDC2 has been shown to regulate cell migration by enhancing adhesion and proliferation of cancer cells and fibroblasts." (PMID 22900087, 2012). "Therefore, SDC2 methylation can be detected in detached cancer cells." (PMID 39717169, 2024). "SDC2 could regulate cell migration and angiogenesis in cancer." (PMID 35127947, 2022). "Therefore, shed syndecan-2 may enhance angiogenic processes, thereby facilitating cancer cells growth and metastasis." (PMID 25686828, 2015). "Cell surface heparan sulfate proteoglycans (HSPGs), namely, syndecan-1 (SDC1), SDC2, and SDC4, are involved in cancer progression, metastasis, and regulate extracellular vesicles (EVs) biogenesis, including the microvesicles (MVs)." (PMID 40940401, 2025). "SDC2 gene has a promoter methylation rate of 89.4% in cell‐free DNA of CRC patients and 81.1% in adenoma stage cancer patients." (PMID 37881109, 2023). "The top outgoing signaling from epithelial cancer cells to CAFs (communication probability > 0.10) showed interactions between MIF (cancer cells) and CD74 + CD44 (CAFs) or MDK (cancer cells) and NCL/SDC2/LRP1 (CAFs)." (PMID 36352420, 2022). "Interestingly, this study implies that MMP-7 activity can be specifically regulated through a direct interaction with SDC2 on the cancer cell surface, and that blocking this activating interaction could be a means to specifically inhibit the enzymatic activity of MMP-7." (PMID 35682569, 2022). "Here we outlined the remarkable features of HSPGs, such as GPC1, GPC4, GPC5, SDC1, SDC2, SDC3 and HSPG2, and some HSPG-related proteins like heparanase and SULF1/2, in cancer diagnosis." (PMID 34249755, 2021). "In conclusion, six core genes including COL3A1, EEF2, FN1, PTPRF SDC2, and RAC1, and several cancer-related metabolic processes, signaling pathways, and overall survival rate of patients were identified in BM PCa." (PMID 34229299, 2021). "Recently, many epigenetic biomarkers have been studied in cancer diagnosis, including hMLH1, E-cadherin, CDKN2A, CDKN2B and APC in GC and SEPT9, SFRP2, THBD, SDC2, VIM and FBN1 in CRC." (PMID 29137404, 2017). "Of the genes tested in plasma, BCAT1, GRASP, IKZF1, IRF4, SDC2, SEPT9 and SOX21 exhibited high sensitivity (≈55% or greater) for detection of methylated ctDNA in cancer patients." (PMID 27983717, 2016). "It exerts a significant inhibitory effect on the expression of SDC2 and SDC4 in cancer cells, which leads to suppression of cell growth ability, migration, and invasion." (PMID 26293675, 2015). "In CXCL12 synovial fibroblast cells from RA patients, SDC2 was found to have a role in extracellular matrix remodeling, suggesting that IRF1 may have a similar role in cancer." (PMID 40862725, 2025). "This suggested that if SDC2 has a role in cancer, it is not in the luminal cells, but in mast cells and in FB2 fibroblast cells." (PMID 40862725, 2025).
cancer (continued). "Fallen cancer cells can appear in both feces and blood, which may be the reason why the sensitivity and specificity of SEPT9 and SDC2 methylation are similar in feces and blood." (PMID 39717169, 2024). "DNA microarray analysis of CRC samples revealed a high methylation rate of approximately 95% for the SDC2 gene, regardless of the cancer stage." (PMID 37881109, 2023). "Among these, we found interactions that may constitute potential targets for CAFs-based therapies, such as THBS2/THBS3 (myCAF2) and CD47 (cancer cells) or between MDK (CAFs) and SDC2/SDC4/NCL (cancer cells)." (PMID 36352420, 2022). "Glypican proteoglycan (GPC1 and GPC6), core membrane-anchored heparan sulfate proteoglycans, were upregulated in ESCC tissues compared with para-carcinoma tissues, whereas syndecan proteoglycans (SDC1, SDC2, and SDC4), transmembrane heparan sulfate proteoglycans, were downregulated." (PMID 35840985, 2022). "This was reflected in the syndecan-2 interactome where the largest group was “cell communication”, the top disease enrichment was “cancer” and “cardiovascular”, and the top KEGG pathway was “proteoglycans in cancer”." (PMID 32984315, 2020). "Consistently, Niu and colleagues detected in tissue specimens a very high frequency of SDC2 promoter hypermethylation in 83% of the CRC tumors (103/124) and further demonstrated that methylation level was higher in 96.8% (120/124) of cancers than in their paired adjacent normal epithelia." (PMID 33126908, 2020). "Interestingly, several genes, such as DRAM1, SERPINE2, SDC2 and CTSB, have been shown to correlate with chemotherapy efficiency in cancers 20-24." (PMID 31660072, 2019). "Some TSGs, including GSTP1, MGMT, CDH1, P16, RAR-β2, septin 9 (SEPT9), syndecan 2 (SDC2), cyclin-dependent kinase inhibitor 2A (CDKN2A), and short stature homeobox 2 (SHOX2), have been validated to be silenced through DNA methylation in various types of cancer." (PMID 32075099, 2020). "Even in this case, the present study provides the first evidence for such a prognostic relationship in any cancer type and, similarly to the potential of NG2/CSPG4, emphasizes that SDC2 may serve as a putative target for prevention and/or treatment of relapsing oral cavity HNSCC." (PMID 25935541, 2015). "Since the interaction of SDC2 with MMP-7 is important to regulate cancer activity, and 50 nM of S2P showed anticancer activity both in vitro and in vivo, we further investigated whether 50 nM of S2-D and S2-FE could inhibit the cancer activity of HT29-SDC2 cells." (PMID 35682569, 2022). "Unlike the tumorigenic behaviors of SDC2 in colon cancer cells, TFPI2 has been shown as a tumor suppressor gene in several malignant tumors." (PMID 35227195, 2022).
infection (5 papers, 2011 to 2025). The state of being infected such as from the introduction of a foreign agent such as serum, vaccine, antigenic substance or organism. "There are four different human syndecans, SDC1, SDC2, SDC3, and SDC4, which are implicated in the infection of many different viruses." (PMID 40569080, 2025). "Future studies are warranted to further determine the molecular basis underlying the role of SDC2 and other members of HSPGs in HBV cell attachment and infection." (PMID 40569080, 2025). "Further exploration is needed to clarify the roles played by the syndecan-2 released in ETBF infection." (PMID 34769248, 2021). "Although molecular components of the gut epithelial barrier such as metalloproteinase-7 (MMP-7) and syndecan-2 are known to be associated with inflammation, little has been reported about MMP-7 expression and syndecan-2 shedding in response to ETBF infection." (PMID 34769248, 2021). "Together these findings suggest that MPA has no direct effect on HIV binding to epithelial cells or infection of T cells, but that the increased SDC2 expression associated with high dose MPA promotes HIV capture and transfer to immune cells." (PMID 25798593, 2015). "However, nothing has been reported about the role of syndecan-2 in ETBF infection until the results of this study, which is the first report to elucidate the role of syndecan-2 in ETBF infection." (PMID 34769248, 2021). "Future exploration is needed to clarify whether ETBF infection affects MMP-7 expression and syndecan-2 release in vivo and whether the released syndecan-2 regulates the pro-MMP-7 activation process in BFT-exposed IECs." (PMID 34769248, 2021).
adenocarcinoma (4 papers, 2013 to 2025). A common cancer characterized by the presence of malignant glandular cells. "In adenocarcinomas, positive immunostaining for SDC2 was detected, with moderate immunostaining present throughout the cytoplasm of neoplastic epithelial cells of patients with Gleason 3 tumors and strong cytoplasmic and pericellular immunostaining in Gleason 4–5 tumors." (PMID 34445387, 2021). "Our study also found that the methylation level of SDC2 was significantly higher in the faeces of patients with CRC than in normal patients, while the methylation level of adenocarcinoma was > AA > AD > polyp/normal." (PMID 37783044, 2023).
autosomal dominant disease (1 paper, 2018). Autosomal dominant form of disease. "Microduplication of chromosome 8q22.1 is mainly associated to Leri's pleonosteosis syndrome phenotype, an extremely rare autosomal dominant disease encompassing the GDF6 and SDC2 genes." (PMID 30123278, 2018).
digestive system cancer (1 paper, 2026). A primary or metastatic malignant neoplasm involving any part of the digestive system. "Notably, the SDC2 marker displayed zero false positives among 98 digestive system cancer cases within the control groups, while SFRP2 and TFPI2 showed 8.16% and 10.2% false-positive rates, respectively." (PMID 41695361, 2026).
heart disease (1 paper, 2020). "Overall, this could point to a role for syndecan-2 and the CAVINs in heart disease." (PMID 32984315, 2020).
SDC2 also shares sentences with these, for which no sentence is quoted: pneumonia (4 papers); Arthritis (3); brain tumors (3); COVID-19 (3); esophageal squamous cell carcinoma (2); head and neck squamous cell carcinoma (2); idiopathic pulmonary fibrosis (2); lung adenocarcinoma (2); malignant thyroid tumors (2); pancreatic ductal adenocarcinoma (2); acute coronary syndrome (1); acute respiratory distress syndrome (1); alveolar rhabdomyosarcoma (1); Alzheimer disease (1); astrocytoma (1); autism spectrum disorder (1); autoimmune hepatitis (1); bone metastasis (1); Cachexia (1); cholestasis (1); colon adenocarcinoma (1); diabetic cardiomyopathy (1); diabetic nephropathy (1); endometriosis (1); endotoxemia (1); glioblastoma (1); glomerular diseases (1); head and neck cancer (1); hepatocellular carcinoma (1); inflammation (1).
A further 18 diseases each share a sentence with SDC2 in 1 paper.